IFNA2 (interferon alpha 2)
Diseases named in the same sentence as IFNA2 in open-access papers (continued):
Sharing a sentence is not in itself a finding about the gene and the disease.
neuroendocrine tumors (2 papers, 1994 to 2018). "For many years, interferon alpha-2b and octreotide analogs were considered the pillars of treatment for patients with gastroenteropancreatic neuroendocrine tumors." (PMID 29892268, 2018). "As MPPGs are also neuroendocrine tumors, occasionally patients were also treated with interferon alpha-2b." (PMID 29892268, 2018). "Interferon alpha-2b activates natural killer cells that can recognize and destroy cancer cells and has been used for the treatment of patients with gastroenteropancreatic neuroendocrine tumors, melanoma, and kidney cancer." (PMID 29892268, 2018). "Twenty-nine patients with adenocarcinomas of gastrointestinal or unknown primary, and three with advanced neuroendocrine tumours, were entered into a study of bolus plus infusional 5-fluorouracil (FUra) modulated with high-dose leucovorin (LV) and recombinant interferon alpha 2a (IFN-alpha)." (PMID 7917927, 1994).
osteoporosis (2 papers, 2019 to 2024). A condition of reduced bone mass, with decreased cortical thickness and a decrease in the number and size of the trabeculae of cancellous bone (but normal chemical composition), resulting in increased fracture incidence. "The levels of cytokines (IFN-γ, IFNα2, IL-33, IL-12p70, IL-12p70) and MCP-1 in plasma were significantly higher in the osteoporosis group." (PMID 38817601, 2024). "Overall, our findings showed that in a group of apparently healthy postmenopausal women, cytokine levels of IFNα2, IFN-γ, IL-12p70, IL-33 and MCP-1 were significantly higher in groups with low bone mass (osteoporosis) than those with higher bone mass (osteopenia and healthy)." (PMID 31333751, 2019).
ovarian carcinoma (2 papers, 1990 to 2009). A malignant neoplasm originating from the surface ovarian epithelium. "The systemic administration of recombinant interferon alpha-2b to 15 patients with ovarian cancer and different basal levels of TAG 72 did not increase serum levels of the antigen." (PMID 2167724, 1990).
sarcoidosis (2 papers, 2020 to 2024). Sarcoidosis is a multisystemic disorder of unknown cause characterized by the formation of immune granulomas in involved organs. "IFNα2 was detected in 74 % and 64 % of patients with sarcoidosis and pulmonary TB, respectively, while IFNγ was found in 78 % and 23 % of patients with sarcoidosis and TB, respectively." (PMID 39309852, 2024). "In contrast to TB, sarcoidosis was associated with increased serum IFNγ levels and both IFN-I and II activity, as well as elevated serum IFNα2 in SU compared to those in TBU." (PMID 39309852, 2024). "Detectable levels of IFNα2 were present in 14 out of 22 (64 %) serum samples from patients with TB, 20 out of 27 (74 %) patients with sarcoidosis and 28 out of 32 (88 %) HCs." (PMID 39309852, 2024). "Furthermore, patients with TB had significantly (p < 0.0001) higher anti-IFNα2 and anti-IFNγ autoantibody levels than in patients with sarcoidosis; however, these concentrations were comparable to Indonesian HCs." (PMID 39309852, 2024). "Observed levels of anti-IFNα2 autoantibodies in HCs, sarcoidosis, and TB were substantially lower compared to the level of anti-IFNα2 observed in a patient with APECED (MFI = 29380) and anti-IFNγ in a patient with AOID (MFI = 33381) as detected at a 1000-fold serum dilution." (PMID 39309852, 2024). "Although no statistical significant difference in serum IFNα2 concentration was observed between total TB and sarcoidosis groups, patients with TBU had significantly lower serum IFNα2 concentrations (median = 0.05 pg/mL) than that in patients with SU (median = 34.70 pg/mL; p = 0.004)." (PMID 39309852, 2024).
Stroke (2 papers, 2019 to 2025). Sudden impairment of blood flow to a part of the brain due to occlusion or rupture of an artery to the brain. "The seven important predictor genes (CCR4, IFNA2, IL-9, IL-7, IL-5, CCR3, and IL-27) that overlapped both stroke outcomes had mean fold change ranging from 3.98 to 35.06." (PMID 32010048, 2019). "The intersection of the top 10 genes from the two stroke outcomes are seven genes with T2DM, these include CCR4, IFNA2, IL-9, IL-7, IL-5, CCR3, and IL-27." (PMID 32010048, 2019).
aplastic anemia (1 paper, 2010). Anemia resulting from bone marrow failure (aplastic or hypoplastic bone marrow). "Our case clearly shows that the causative role of pegylated interferon alpha 2a in the development of aplastic anemia must not be ignored." (PMID 20704699, 2010).
autoimmune thyroiditis (1 paper, 1990). "The possibility of autoimmune thyroiditis should be anticipated in future trails combining interleukin-2 and interferon alpha-2a." (PMID 2390468, 1990).
Bell's palsy (1 paper, 2013). Partial or complete paralysis of the facial muscles of one side of a person's face. "Here we present another case report indicating Bell’s palsy during interferon alpha 2a treatment in Behçet uveitis." (PMID 24715961, 2013).
chronic viral hepatitis (1 paper, 2010). "IFN lambda in association with ribavirin and/or IFNα2 holds considerable promise for the treatment of chronic viral hepatitis with the prospect of less side effects than current treatment options." (PMID 27713294, 2010). "Recombinant analogues of IFNα2 and IFNβ1, and more recently pegylated forms of IFNα2, have found wide application for the treatment of chronic viral hepatitis and remitting relapsing multiple sclerosis (RRMS) respectively." (PMID 27713294, 2010). "Three IFN sub-families, type I, II, and III IFNs have been identified in man, Recombinant analogues of type I IFNs, in particular IFNα2 and IFNβ1, have found wide application for the treatment of chronic viral hepatitis and remitting relapsing multiple sclerosis respectively." (PMID 27713294, 2010).
colon adenocarcinoma (1 paper, 2014). "For colon adenocarcinoma, the somatic mutations in four genes were significantly enriched in protein pocket regions: B2M (P = 3.1 × 10-4), IFNA2 (P = 3.1 × 10-4), VAV3 (P = 6.6 × 10-4), and ETV6 (P = 1.0 × 10-3)." (PMID 25360158, 2014).
dermatitis (1 paper, 2015). An inflammatory process affecting the skin. "Concentrations of IFNα2 decreased in our aging subjects, an observation that might be in good agreement with the increase in dermatitis observed in aging skin, and could possibly represent a slowly declining innate immunity that does not yet have pathologic significance." (PMID 26035055, 2015).
diabetic macular edema (1 paper, 2020). "This case series demonstrated the potential efficacy of interferon alpha 2b in the treatment of refractory diabetic macular edema." (PMID 33133435, 2020).
Down syndrome (1 paper, 2021). "With the exception of IFNA1 expression, type I interferons (IFNA2 and IFNB1) were all upregulated, indicating that the axis IFNAR-STAT-OAS is upregulated in Down syndrome." (PMID 33479353, 2021).
epithelioid hemangioendothelioma (1 paper, 2024). A low-grade malignant blood vessel neoplasm. "Interferon alpha-2B has been used as a successful adjunct therapy to LRx in the treatment of multifocal epithelioid hemangioendothelioma with metastatic potential." (PMID 38844684, 2024).
glioblastoma (1 paper, 2025). The most malignant astrocytic tumor (WHO grade IV). "Next, we co-transfected human immune cells with mRNA encoding ZsGreen and mRNA encoding the human NKG2D CAR, human cytokines (IL-12 and IFNα2), or both, CAR and cytokines, and co-cultured them with glioblastoma patient samples ex vivo." (PMID 39889712, 2025).
herpes simplex virus keratitis (1 paper, 2023). A superficial, epithelial Herpesvirus hominis infection of the cornea, characterized by the presence of small vesicles which may break down and coalesce to form dendritic ulcers (keratitis, dendritic). "Recombinant human interferon alpha-2b eye drops, indicated for the treatment of herpes simplex virus keratitis, have spectroviral activity, can quickly reach the site of the lesion, protect target cells, and prevent the spread of the virus, effectively killing it." (PMID 38293295, 2023).
Hypoalbuminemia (1 paper, 2021). The concentration of albumin in the blood circulation is below the lower limit of normal. "For example, high IFNA2 (Stage 1 marker) and strong hypoalbuminemia (Stage 2 marker) have been independently associated with risk of severe COVID19." (PMID 33724185, 2021).
Insulin resistance (1 paper, 2016). Increased resistance towards insulin, that is, diminished effectiveness of insulin in reducing blood glucose levels. "The aim of this study was to assess the effect of insulin resistance on the development of HCC by non-cirrhotic chronic hepatitis C patients treated with pegylated interferon alpha-2b (PEG-IFNα2b) and ribavirin." (PMID 26913058, 2016).
liver cancer (1 paper, 2021). An epithelial or non-epithelial malignant neoplasm that arises from the liver. "Liver cancer, most commonly known as hepatocarcinoma, is a common malignancy, and treatment of this cancer with interferon-alpha 2A (IFN-α) has a relatively poor response rate of about 30%." (PMID 34221501, 2021).
lung carcinoma (1 paper, 2023). "In this work, we reveal a novel regulatory mechanism involving enhancer clusters in the upregulation of TRAIL upon IFNα isoform 2 (IFNα2) stimulation of breast and lung cancer cells." (PMID 36765925, 2023).
mast cell leukemia (1 paper, 2013). Mast cell leukemia is a malignant form of systemic mastocytosis (SM) characterized, most of the time, by the presence of circulating mast cells. "Those with ASM and mast cell leukemia (MCL) may have some benefit from cytoreductive therapies (e.g. interferon alpha-2b or cladribine), although the disease usually recurs and the long-term prognosis is poor." (PMID 23903270, 2013).
myeloproliferative neoplasm (1 paper, 2025). A clonal hematopoietic stem cell disorder, characterized by proliferation in the bone marrow of one or more of the myeloid (i.e., granulocytic, erythroid, megakaryocytic, and mast cell) lineages. "Interferon alpha-2 treatment reduces circulating neutrophil extracellular trap (NETs) levels that may play a pathogenic role in the thrombosis in myeloproliferative neoplasms." (PMID 41228273, 2025).
polycythemia vera (1 paper, 2022). "Today, a novel interferon alpha-2b formulation (Besremi) is marketed for treatment of the MPN disease polycythemia vera." (PMID 36428587, 2022).
psychotic disorder (1 paper, 2026). An abnormal condition of the mind that involves a loss of contact with reality. "In contrast, there was a significant decrease in IFNα2 and IL-4 cytokine levels in ASD compared to both controls and psychotic disorders." (PMID 42239763, 2026).
pulmonary hypertension (1 paper, 2014). Increased pressure within the pulmonary circulation due to lung or heart disorder. "Human recombinant interferon alpha 2b was a kind gift from John Kirkwood, M.D. The HPASMC and HPAEC from IPAH patients as well as the control and IPAH serum were from the Pulmonary Hypertension Breakthrough Initiative of the Cardiovascular Medicine Research Fund." (PMID 24837600, 2014).
rheumatoid arthritis (1 paper, 2013). A chronic, systemic autoimmune disorder characterized by inflammation in the synovial membranes and articular surfaces. "We describe a case of a 35-year-old man, with rheumatoid arthritis (RA) and hepatitis C virus genotype 1a with a liver biopsy in 2001 with a METAVIR score pattern A1 F0; he received interferon alpha 2b for six months, but treatment was suspended because of reactivation of RA." (PMID 25431703, 2013).
rosacea (1 paper, 2023). A chronic erythematous skin disorder that affects the face. "When comparing acute flare-ups with stabilized chronic lesions of rosacea in order to identify potentially unique patterns, we found a selective and significant increase in expression of type I IFNs IFNA2 and IFNB1 in flare-ups." (PMID 36633910, 2023).
Splenomegaly (1 paper, 2011). Abnormal increased size of the spleen. "However, protection against splenomegaly was significantly improved when mice had been co-administered vectors encoding IFNα2, IFNα4, IFNα6 or IFNα9 (P < 0.05)." (PMID 21943056, 2011). "Only the co-administration of adenoviral vectors encoding IFNα2, IFNα4, IFNα6 and IFNα9 resulted in strongly improved immune protection of vaccinated mice from subsequent FV challenge infection with high control over FV-induced splenomegaly and reduced viral loads." (PMID 21943056, 2011).
Thrombocytosis (1 paper, 2013). Increased numbers of platelets in the peripheral blood. "This degree of disease control with interferon is in accordance with findings of previous studies, which established that interferon-alpha 2a adequately controls thrombocytosis and vasomotor symptoms in ET." (PMID 24385783, 2013).
thyrotoxicosis (1 paper, 2023). A hypermetabolic syndrome caused by the elevation of thyroid hormone levels in the serum. "Elevated levels of IFNa2 at T0 and IL-5 at T2 were associated with the progression of thyrotoxicosis." (PMID 37629267, 2023).
uterine infection (1 paper, 2022). "The top three upstream regulators predicted to be activated in the endometrium of pregnant cows after uterine infection include 1) IFNG (cytokine); 2) IFNA2 (cytokine); and 3) PRL (cytokine)." (PMID 35358206, 2022).
vaginal infection (1 paper, 2024). "Finally, our in vivo results show excellent antiviral efficacy of Interferon Vaginal Tablets containing interferon alpha 2-b in controlling HSV-2 using a murine model of vaginal infection." (PMID 38932280, 2024).
infection (117 papers, 2009 to 2026). The state of being infected such as from the introduction of a foreign agent such as serum, vaccine, antigenic substance or organism. "We did find that induction of both IFN-β and IFNα2 transcripts was increased after infection with UL88-deficient HCMV, indicating that Type I IFNs could be the exogenous factor that slows HCMV spread in MyD88-transduced cultures." (PMID 40638072, 2025). "The induction of type 1 interferon responses, the mRNA expression of the genes encoding interferon alpha-2 and interferon-induced proteins viperin and RNA dependent protein kinase, have been determined in the previously conducted infection trials from the same experimental study." (PMID 37465154, 2023). "Vero cells were infected with either M114 or V114 viruses at MOI 5.0 and at 24 hours post-infection (hpi), cells were either exposed to 103 IU/mL recombinant human IFNα2 for 30 mins or left unexposed." (PMID 35536870, 2022). "Our analyses indicated that despite the presence of baseline inflammation, 2 yr old mice had significantly lower induction of innate immune genes at 2 days post-infection, including Il6, Ccl4, Cxcl10, Rig-I, Irf7, Ifna2, Oas1b, and Mx2." (PMID 36679892, 2022). "When performing an analysis focusing on inflammation and infection associated factors in IPA, we found a strong Z-score for IFNβ, IFNA2, IRF1, and IRF7 signaling." (PMID 36032117, 2022). "At day 3 post infection there was an increase in Ifnα2, Isg15, and Stat1 gene expression detected in young adult lung in response to either H1N1 or H3N2." (PMID 34829979, 2021). "By days 5 and 7 of infection, there was a marked difference in gene expression with heightened expression of Mx1, Tlr3, Ifnα2, Ifnαr1, Ifnβ1, and Il-15 detected in aged lung in response to H1N1." (PMID 34829979, 2021). "Consistently, the relative expression of Ifna2, Ifna4 and Ifnb1 was highly decreased in the spleen and LN 16 h post-infection in CD169-Cre+/ki x Usp18fl/fl mice." (PMID 32210083, 2020). "D39 infection was capable of inducing expression of IFNβ and IFNa2 (subtype of IFN-I) at both 1 and 5 h compared to D39ΔspxB infection." (PMID 30984149, 2019). "Pre-treatment of A549 cells with catalase prior to D39 infection resulted in diminished IFNβ and IFNa2 transcript levels, in which 5-fold reduction was observed in IFNβ and IFNa2 transcript levels at 5 h post-infection." (PMID 30984149, 2019). "MOPV infection of mDCs induced a 10- (IFNα1) to 80- (IFNα2) fold increase in IFN-I production relative to that of mock-infected cells when cocultured with T cells." (PMID 30419076, 2018). "In human MDM, IFNα2 and TNFα were both elevated 2–5 dpi in 17D-infected cells, but the response diminished as the infection proceeded." (PMID 27191161, 2016). "Specifically, IL-1RA, IFNα2 and TNFα were all elevated within the first five days of infection relative to mock-infected controls, but there was little difference in expression between Asibi virus- and mock-infected MDM." (PMID 27191161, 2016). "Kornbluth and collaborators demonstrated that macrophages treated 18 hours with 1000 IU/ml of IFNα2 prior to HIV-1 NL4-3BaLenv strain infection inhibited viral production." (PMID 22140520, 2011). "These ISGs included Ifna2, Ifna4, and Ifnb1, which were induced to high levels in all four strains at 12 hours (>1000-fold) and 24 hours (>100-fold) post-infection, and likely represent early IRF3-mediated gene expression." (PMID 21379341, 2011). "Notably, activated MG 1 was the primary cell type expressing genes encoding RIG-I (Ddx58) and MDA5 (Ifih1), PRRs important in alphavirus sensing, along with type I IFN genes Ifnb1 and Ifna2 throughout infection." (PMID 39749347, 2024). "In a retrospective study of patients receiving IFNα2 through inhalation, alone or in combination with other drugs at a relative early versus late stage of the infection, it was found that those receiving IFNα2 at an early stage had a significantly lower rate of mortality." (PMID 33117408, 2020).